SOD2 (superoxide dismutase 2)
Diseases named in the same sentence as SOD2 in open-access papers (continued):
Sharing a sentence is not in itself a finding about the gene and the disease.
tumor (continued). "Moreover, future work examining the spatio-temporal nature of SOD2 regulation in the context of changing tumor microenvironments is necessary to allows us to better design oxidant- or antioxidant-based therapeutic strategies that target the adaptable antioxidant repertoire of tumor cells." (PMID 29099803, 2017). "Thus we next determined whether [ruxolitinib + MMF] treatment altered the production of reactive oxygen species (ROS) in tumor cells and whether the over-expression of SOD2 or TRX could suppress drug combination toxicity." (PMID 26981780, 2016). "Interestingly, accumulating evidence suggest that reducing oxidative stress levels by increasing SOD2 expression may represent a double-edged sword in tumor development." (PMID 25745358, 2015). "SOD2 may act as a tumor suppressor during the initial onset/proliferative stage of tumor initiation, yet once the tumor progresses to a more aggressive and invasive phenotype, SOD2 levels appear to positively correlate and contribute to enhanced metastatic behavior of cancer cells." (PMID 26439801, 2015). "Sod2+/− mice have been reported to have reduced Mn-SOD activity (~50%) in all tissues throughout life, increased oxidative damage as demonstrated by elevation of 8-OHdG in all tissues (significantly higher compared with WT mice), and increase in tumor incidence." (PMID 23936608, 2013). "Studies suggested that alteration in SOD2 level may influence the metastatic potential of tumor cells via activating mitogen-activated protein kinases (MAPK), and regulating the expression of matrix metalloproteinase (MMP) gene family members (including MMP-1 and MMP-9)." (PMID 20618948, 2010). "Conversely, reduced SOD2 expression in early-stage PTEN-null thyroid and pancreatic carcinogenesis models increases DNA damage and tumor initiation, indicating a tumor-suppressive role during early malignant transformation." (PMID 40867898, 2025). "In our study, we demonstrate that SOD2 overexpression is critical for preventing QCC reactivation by inducing apoptosis, suppressing recurrent tumor growth, and prolonging survival in preclinical models." (PMID 40520023, 2025). "While investigating the tumor-promoting mechanism of KYNU, we found that superoxide dismutase-2 (SOD2) interacts with KYNU and is highly expressed in a coculture system." (PMID 40616124, 2025). "Targeting tumor redox homeostasis, via inhibition of GSH/SOD2 biosynthesis or induction of their metabolic depletion, represents a promising therapeutic strategy to potentiate anticancer drug efficacy." (PMID 40563367, 2025). "M2 macrophage-secreted KYNU induced malignant behavior and stemness via the SOD2-mtROS-ERO1α-UPRER pathway, contributing to a positive feedback loop for tumor cell self-protection." (PMID 40616124, 2025). "We analysed the changes in antioxidant (SOD1, SOD2, CAT, GPX1, HIF-1α, and NRF2) and anti-inflammatory nuclear factor kappa B (NF-κB) gene expression in tumour-bearing mice." (PMID 39506978, 2024). "In this study, we observed that PDL1, PD1, SOD2, PARP, SET, TGF-ß, NF-kB, and BCL2 were highly expressed in the control tumor tissue." (PMID 38258094, 2024). "Significant positive correlations with GPX4 (ferroptosis), ACSL4 (fatty acid metabolism), SOD2 (antioxidant), HIF1A (tumor growth and metastasis), FAT1 (fatty acid metabolism) and IREB2 (Iron-responsive element)." (PMID 38206305, 2024). "Many tumor suppressors and oncogenes modulated by H2A.J play important roles in the regulation of energy metabolism (IGFBP3; IGFBP4; IGFBP5; AKR1B1; SOD2)." (PMID 39062630, 2024). "Mechanistically, secreted IGFBP1 activates mitochondrial superoxide dismutase (SOD2) by preventing AKT1‐mediated SOD2 phosphorylation, thereby promoting metastasis by sustaining tumor cell survival during confined migration." (PMID 37296072, 2023).
tumor (continued). "They found that antioxidant enzymes including SOD2 and CAT were decreased, while DNA repair enzymes were imbalanced (i.e., were both over- and under-expressed when compared to non-tumor tissue), and this abnormality generated MSI." (PMID 37835526, 2023). "It has been suggested that superoxide dismutase 2 (SOD2) can be independently regulated by cigarette smoke and HPV, increasing adaptation to OS and tumor progression." (PMID 37108069, 2023). "SOD2 expression was enriched among stage II (3.57-fold) and advanced-stage (III/IV) (7.36-fold) tumor tissues relative to normal breast tissues." (PMID 35017469, 2022). "The phenomenon of increased SOD2 levels and decreased CAT levels has previously been observed in tumor cells from advanced stages of disease and has been shown to promote tumor cell proliferation and invasive and migratory phenotypes." (PMID 36264639, 2022). "An even more pronounced effect of decreased tumor growth and increased animal survival was achieved in MIA PaCa-2 cells when SOD2 and GPX1 were overexpressed simultaneously." (PMID 36552527, 2022). "Decreased SIRT3 was found to decrease IDH2 and SOD2 hyperacetylation by increasing the level of reactive oxygen species, suggesting that SIRT3 acts as a tumor suppressor in B cell malignancies." (PMID 36230534, 2022). "As Nrf2, also FOXM1 activated the antioxidant proteins SOD2 and CAT in MPM cells towards HMC, so counteracting oxidative stress in tumor cells." (PMID 33799965, 2021). "Because ROS levels are regulated by multiple antioxidant enzymes, including Mn‐containing SOD2 in the mitochondrial matrix, we first analysed TCGA database by GEPIA and explored the correlations between LETM1 and SOD2 in CRC tumours." (PMID 33314691, 2021). "Next to radiation, also manganese superoxide dismutase (MnSOD or SOD2) is able to activate NF-κB and contributes as such to an aggressive tumor phenotype." (PMID 34041023, 2021). "In contrast, overexpression of either SOD2 or OGG1 suppresses oxidative stress-induced EBV DNA damage, thus preventing the HKDC1 interruption-induced suppression of EBV and tumor growth." (PMID 33423158, 2021). "For instance, it is plausible that the downregulation of 3 upstream regulators of SOD2 (IGFBP7, KL, BTG2), which are potential tumor suppressors, leads to an increase in SOD2 when the malignancy of IPMN worsens." (PMID 32842508, 2020). "We found the resistant tumor (GBM#1), which expressed significant TIC biomarkers, also had higher SOD2 expression." (PMID 31629402, 2019). "When SOD2 was downregulated following by TMZ treatment, cell apoptosis was enhanced with less colony formation, tumor initiation and survival." (PMID 31629402, 2019). "During this process, genes such as SOD2, MMP19, SLC2A3, and SLPI were also upregulated, all of which were related to the invasion and migration of tumor cells." (PMID 31487431, 2019). "Our results indicate that tumor tissue has greater total protein carbonylation, lower SOD1 and SOD2 protein levels, lower total SOD activity, and higher LC3-II levels compared to adjacent healthy tissue." (PMID 29596499, 2018). "Of the four tumor tissue samples, only one tumor sample from a 61-year-old subject showed greater SOD1 levels, but SOD2 levels were lower than the respective healthy tissue sample." (PMID 29596499, 2018). "Overexpression of mitochondrial SOD2 acts as a tumor suppressor in skin and breast cancers, suggesting that high SOD activity promotes tumor initiation." (PMID 28744456, 2017). "Low SIRT3 expression and subsequent hyperacetylation and inactivation of SOD2 are thought to play a major role in the O2•−-driven activation of HIF-1α, leading to increased glycolysis in tumor cells." (PMID 29099803, 2017). "PKM2 knockdown inhibited cell migration and invasion, reduced SOD2 (manganese superoxide dismutase) activity and the intracellular H2O2 level, and inhibited tumour growth and lung metastasis in vivo." (PMID 28978113, 2017).
tumor (continued). "Immunofluorescence analysis revealed a strong increase in signal intensity for mitochondrial SOD2 and peroxisomal Catalase in the tissues from the CAP-injected tumor bearing mice, compared with the control group." (PMID 27775662, 2016). "On the other hand, in tumor cell lines the early increase of SOD1 and SOD2 levels was followed by a strong reduction of both protein expression after 72 hours of treatment." (PMID 27280849, 2016). "On the other hand, low SOD2, higher Serum AFP, tumor embolus, multiple tumors, advanced TNM, BCLC, and postoperative metastasis were statistically significantly correlated with shorter RFS in HCC patients." (PMID 27221200, 2016). "Inactivation of the protective signaling pathways also lowers the expression of the detoxification enzymes SOD2 and TRX which additionally facilitates sustained high levels of toxic ROS, all collectively leading to tumor cell death." (PMID 26981780, 2016). "In this study, we show that SOD2 expression is commonly reduced in HCC, suggesting that it primarily has a tumor suppressive function in liver tumorigenesis." (PMID 27221200, 2016). "Genes involved in DNA damage response were differentially up-regulated in the sensitive tumours (FBXO6, RFC5, SOD2) suggesting that preparedness for keeping DNA undamaged promotes sensitivity when encountering a drug that causes DNA damage (CHO)." (PMID 25881228, 2015). "Collectively, these findings demonstrate that ZGE modulates multiple stress‐responsive pathways in tumor tissues, attenuating oxidative damage (via TRPM2 and SOD2), amplifying inflammatory signaling (via TNF‐α), and promoting apoptosis (via caspase‐3), particularly when combined with DOX treatment." (PMID 41306344, 2025). "Superoxide dismutase 2 (SOD2), a mitochondrial superoxide scavenger and H2O2 regulator, may affect tumor development in the TME by regulating oxidative stress levels." (PMID 40568576, 2025). "S100A9, which we found up-regulated in pT1-HG biopsies, was identified as a protein associated with iNOS activity, and it is also involved in the regulation of signal transduction, such as SOD2, APOA1, HSP90, HSPA5, HINT1, MYDGF, and SerpinB3, and in immunomodulation in tumor microenvironments." (PMID 41441336, 2025). "The increased abundance of SOD2 and SDHB suggests an enhanced tumor-suppressing effect of ST1926." (PMID 40429796, 2025). "In this study, we aimed to investigate whether SOD1 and SOD2 expression levels in OPC tissues influence disease progression, including primary tumor progression, lymph node metastasis, and survival prognosis." (PMID 40244057, 2025). "Additionally, it was suggested that miR-21 influences the tumor microenvironment by modulating antioxidant enzymes like SOD2 and GPx1, as well as signaling suppressors SOCS1 and SOCS6, thereby promoting conditions favorable for tumor growth." (PMID 41465462, 2025). "In the tumor tissues obtained from the MKN45 cell xenograft model, the tEx(D) treatment led to the most substantial reduction in the expressions of the antioxidant enzymes SOD2 and catalase (p < 0.05)." (PMID 39201449, 2024). "Using tumor samples derived from the tumor xenograft mouse model, we demonstrated that the expression of FSP1, ki67, SOD2, and ACSL4 proteins was significantly suppressed in the FSP1 inhibition and combined treatment groups compared with that in the control group." (PMID 38206305, 2024). "Conversely, SOD2 positive regulation goes hand in hand with an improvement in the elimination of O2− and intracellular H2O2 increase, which correlates with adaptation to OS and activation of signaling pathways involved in tumor progression." (PMID 37108069, 2023). "In addition, by mimicking survival rate analysis widely used in tumor biology, we found that LTF and SOD2 were prognostic factors of gestational age, with higher levels denoting shorter gestational age." (PMID 36966172, 2023).
tumor (continued). "Cancer cells from the MCF-7, U118, and MIA PaCa-2 lines found to overexpress SOD2 when injected into nude mice showed significantly lesser and slower tumor development and decreased mortality when compared with the same cell lines without SOD2 overexpression." (PMID 36552527, 2022). "Upregulated SOD2 levels enhance the oxidation of PTEN and PTP-N12, further activating Akt and p130 cas/Rac1 signaling pathways, respectively; these pathways regulate the hallmarks of cancer during tumor progression." (PMID 35164076, 2022). "The avoidance of H2O2 overproduction is likely to be the cause of no promotion of cancer cells when there is simultaneous overexpression of SOD2 and CAT both in vitro and in vivo and of tumor-preventive and tumor-suppressive effects in the case of the simultaneous overexpression of SOD2 and GPX1." (PMID 36552527, 2022). "Specifically, superoxide dismutase 2 (SOD2) showed a scattered pattern in tumor tissue under IF as opposed to its typical mitochondrial localization in healthy tissue." (PMID 34360635, 2021). "The results showed that SOD2 expression did not correlate with tumor aggressiveness nor SOD2 genotype." (PMID 33535682, 2021). "Consistent with the in vitro results, caffeine significantly inhibited G6PDH enzymatic activity, p-STAT3 signaling activation, and cyclin E, NOX4, and p47-phox (NOX2 regulatory subunit) protein expression, and upregulated the expression of SOD2 protein, in xenografted RCC tumor tissues." (PMID 33123534, 2020). "Finally, co-treatment with TMZ and the SOD inhibitor sodium diethyldithiocarbamate trihydrate in xenograft mouse models with the TMZ-resistant primary tumor resulted in lower tumor proliferation, longer survival, and less CD133, Bmi-1, and SOD2 expression." (PMID 31629402, 2019). "In agreement, the proliferation of the cells by cell density assay was clearly impaired in parental tumor cells by downregulation of SOD2, but not as significant in resistant cells, which the basal level was much higher." (PMID 31629402, 2019). "Another mouse model heterozygous for the Sod2 gene (with decreased Mn-superoxide dismutase activity) does show oxidative injury (increased tumor incidence and DNA damage) but does not decrease longevity." (PMID 31083534, 2019). "Replacement therapy or drug repositioning to target tumor cell mitochondria, as can be achieved with the use of biguanides, should be investigated for the treatment of EAOC with abundant SOD2 expression, which is likely to retain stronger mitochondrial function." (PMID 30700285, 2019). "We found that BA or CDM alone slightly decreased tumor formation, BA/CDM combination additively suppressed tumor formation, SOD2/HIF1C expression (BA/CDM/SOD2/HIF1C) completely diminished the inhibition effect of BA/CDM and largely potentiated tumor growth compared to the CTL group." (PMID 29212263, 2017). "On the other hand, SOD2 overexpression partly diminished the combination effect of BA/CDM, indicating that BA/CDM-mediated ROS formation plays an important role in BA/CDM-mediated tumor suppression." (PMID 29212263, 2017). "The following effects were observed with HK2 knockdown: inhibition of cell migration and invasion; reduced SOD2 activity and intracellular H2O2 levels; suppression of pERK1/2, Slug and Vimentin expression; and inhibition of tumour growth and lung metastasis in vivo." (PMID 27926482, 2017). "We evaluated the combination effect of BA/CDM on tumor suppression through an in vivo xenograft tumor development study using THP1 cells, and we also investigated the potential role of SOD2 and HIF1α through lentivirus-carrying SOD2/HIF1C overexpression in THP1 cells." (PMID 29212263, 2017). "Unlike true tumor suppressors or oncogenes, the SOD2 gene, located on chromosome 6q25.3, is not frequently lost, or rarely mutated or amplified in cancer." (PMID 29099803, 2017).
tumor (continued). "Our results showed that BA/CDM combination additively suppresses in vivo tumor growth in THP1 cells, and overexpression of SOD2/HIF1C diminishes this inhibition effect, indicating that BA/CDM exert additive inhibition effect on tumor growth through ROS generation and HIF1α pathway suppression." (PMID 29212263, 2017). "We evaluated the inhibition effect of BA and CDM on EBV replication through an in vivo xenograft tumor development study using EBV-transformed LCL cells, and we also investigated the potential role of SOD2 through lentivirus-carried SOD2 overexpression or knockdown in LCL cells." (PMID 28977893, 2017). "The result shows that low SOD2 protein expression (p = 0.005), higher serum AFP (p = 0.002), larger tumor size (p = 0.010), multiple tumors (p < 0.001), tumor embolus (p = 0.004) advanced TNM (p = 0.001) and BCLC stage (p < 0.001) are predictors for poor OS of HCC patients." (PMID 27221200, 2016). "Additionally, the down-regulation of H2O2 by either PEG-CAT or si-SOD2 inhibits the activation of the MAPK signaling pathways and tumor invasion, which indicates that H2O2 is the key factor that mediated HG-induced PC metastasis." (PMID 26439801, 2015). "How over-expression of SOD2 impacts on tumor cells survival in advanced cancer is not well understood and needs further investigation." (PMID 24690091, 2014). "We used DNA extracted from tumor tissue rather than non-tumor tissue to assay SOD2 genotype – similar to the Glynn study." (PMID 24498107, 2014). "For example, mitochondrial SOD2 suppresses EMT by regulating ROS homeostasis in specific cancer subtypes; conversely, genetic or pharmacological depletion of SOD2 has been shown to exacerbate tumor progression through compensatory redox imbalances in these contexts." (PMID 40563367, 2025). "Although SOD2 is conventionally characterized as a protective antioxidant, catalyzing the conversion of mitochondrial superoxide radicals into hydrogen peroxide (H2O2) and oxygen (O2) 53, emerging evidence indicates that its overexpression can also exert tumor-suppressive effects 54-58." (PMID 40520023, 2025). "Although it is not understood if SOD2 contributes to tumorigenesis, a possibility is that in aggressive tumor phenotypes, high expression of SOD2 could lead to increased mitochondrial production of H2O2 that activates oncogenic and angiogenic pathways." (PMID 39765891, 2024). "In this case, we also could also observe a negative correlation between tumor volume and SOD2 plasma levels." (PMID 36010852, 2022). "Therefore, this dataset suggests that the relationship between SOD2 plasma levels and tumor volume follows a negative correlation." (PMID 36010852, 2022). "Our results show that regardless of whether a tumor cell is sensitive or resistant to chemotherapy, the changes in the slope of the curve describing the levels of SOD2 correlate well with tumor cell death." (PMID 36010852, 2022). "However, the trend of the curve followed by SOD2 levels at the time of finalizing the treatment was clearly ascending, and therefore following a negative correlation with respected of tumor size." (PMID 36010852, 2022). "In addition, EBF1 exhibits tumor suppressive properties in CCA cells through decrease of stemness and oxidative stress-resistant properties via suppressions of Wnt signaling pathway and antioxidants via inhibition of Oct3/4, SOD2 and CAT expression." (PMID 33854627, 2021). "Moreover, in the spleen of heterotopic tumor model BALB/c mice, ERN, LP-ERN and Tf-LP-ERN nanoparticles increased the expression levels of Nrf2, HO-1, SOD-1 and SOD-2, but reduced the expression levels of P-IKKα+β and P-NF-κB, with Tf-LP-ERN nanoparticles being most effective in this regard." (PMID 34513705, 2021). "Furthermore, we tested whether RNAi can prevent the tumor-like growth in the presence of overexpressed ROS scavengers, which include superoxide dismutase 1 (SOD1), SOD2 and catalase." (PMID 33199523, 2020).